SMC5 (structural maintenance of chromosomes 5)
Diseases named in the same sentence as SMC5 in open-access papers (continued):
Sharing a sentence is not in itself a finding about the gene and the disease.
tumor (5 papers, 2019 to 2026). "In this paper, we also figured out the tumor suppressor function of SMC5 was inextricably linked to the SMC5/6 complex, with the evidence that other components of SMC5/6 complex were also changed after OXA and/or RTX treatment, and these changes followed the same trend as those of SMC5." (PMID 35894836, 2023). "In addition, the Kaplan–Meier curve showed SMC5 was associated with a good prognosis of the tumor (COAD and READ), which suggested that lower expressed SMC5 was more beneficial for the tumor survival." (PMID 35894836, 2023). "Interestingly, examination of publicly available patient data revealed a correlation between very low transcript levels of SMC5/6 and rapid disease progression in squamous lung cancer patients, indicating an association of complex depletion/loss with more aggressive tumours." (PMID 30590722, 2019). "Actually, tumor common mutated genes, like TTN, FAT4, and DNAH2, were highly altered in SMC5 mutation samples, respectively, with the alteration frequency of 100%, 88%, and 81% in COAD, and 100%, 89%, and 83% in READ." (PMID 35894836, 2023). "These indicate that the whole SMC5/6 complex has a tumor suppressive function, and the specific molecular biological mechanisms involved remain to be further investigated." (PMID 35894836, 2023). "We found that deleterious variants-those predicted to cause protein disruption, but not CNAs, in SMC5/6 genes were associated with elevated tumor mutational burden (TMB)." (PMID 42181931, 2026). "SMC5 is a tumor suppressor, that low expression of this gene is benefit for the development of CRC." (PMID 35894836, 2023). "These all demonstrated that SMC5 has the feature of tumor suppressor, that its disorder might contribute to the tumorigenesis and progression of CRC." (PMID 35894836, 2023). "One is lower expressed SMC5 might conduce to tumor evolution and malignant metastasis, the other is downregulation of SMC5 might generate OXA resistance of CRC." (PMID 35894836, 2023). "Our results demonstrate a potential tumor suppressor SMC5 was significantly downregulated in CRC tissues of OXA no‐response patients, which suggested that lower expression of SMC5 may contribute to OXA resistance." (PMID 35894836, 2023).
neurodevelopmental disorder (3 papers, 2020 to 2023). A behavioral and cognitive disorder with onset during the developmental period that involves impaired or aberrant development of intellectual, motor, or social functions. "Mutations of TOP2B lead to neurodevelopmental disorder and diastolic dysfunction, which are phenotypically similar to when SMC5/6 components are mutated." (PMID 38203602, 2023). "Because of the link between SMC5/6 perturbation and neurodevelopmental disorders in humans, we modeled the consequences of SMC5/6 depletion by conditionally mutating Smc5 in the developing neocortex of mice." (PMID 33200984, 2020).
cardiac disease (1 paper, 2023). "Recent work on NSMCE2 and SMC5 demonstrates that the p.Arg372del variant in SMC5 can destabilize the interaction of SMC5 and NSCME2, indicating that SMC5 variants can potentially play a role in heart disease by disrupting its interaction with NSMCE2." (PMID 38203602, 2023).
genetic disorders (1 paper, 2020). "We thus envisage that there remain undiscovered genetic disorders caused by mutations in genes of the SMC5/6 complex that lead to FA or FA‐like disorders and in which the physiological role SMC5/6 in mediating DNA repair and replication termination becomes more apparent." (PMID 31867888, 2020).
SMC5 also shares sentences with these, for which no sentence is quoted: anemia (2 papers); liver cancer (2); primordial dwarfism (2); aortic aneurysm (1); colon adenocarcinoma (1); colorectal carcinoma (1); diabetes (1); insomnia (1); insulin-resistant diabetes (1); lung disease-immunodeficiency-chromosomal breakage syndrome (1); Meiosis (1); Mitral stenosis (1); ovarian carcinoma (1); Promyelocytic Leukemia (1); rectal adenocarcinoma (1); Seckel syndrome (1).